ZNF700 (zinc finger protein 700)
Description:
May be involved in transcriptional regulation.
Synonyms: DKFZp434I1610
Tractability: PROTAC: ubiquitination databases record sites on it.
Gene: Protein-coding gene on chromosome 19 (11,925,068 to 11,950,773, forward strand). Ensembl gene ENSG00000196757.
Subcellular location: Nucleus
Subcellular location (Human Protein Atlas): Nucleoplasm
Pathways (Reactome):
Gene expression (Transcription): Generic Transcription Pathway
Gene Ontology:
Molecular function: DNA-binding transcription factor activity, RNA polymerase II-specific; RNA polymerase II transcription regulatory region sequence-specific DNA binding
Biological process: regulation of transcription by RNA polymerase II; regulation of DNA-templated transcription
Cellular component: nucleus
Genetic constraint (gnomAD): Loss-of-function variants: 38 observed, 68.18 expected, observed/expected ratio (o/e) 0.56, 90% interval 0.43 to 0.73. The upper end of that interval is the gene's LOEUF score, 0.73, which puts it in group 2 of 6, group 1 being the genes least tolerant of losing a copy. Missense variants: 857 observed, 918.27 expected, observed/expected ratio (o/e) 0.93, 90% interval 0.88 to 0.99. Synonymous variants: 285 observed, 295.89 expected, observed/expected ratio (o/e) 0.96, 90% interval 0.87 to 1.06.
Homologues: Orthologues: chimpanzee ZNF700 (99% identical), macaque ZNF700 (94% identical), rat Zfp617 (27% identical), mouse Zfp961 (27% identical). Paralogues in human: ZNF433 (53% identical), ZNF44 (48% identical), ZNF709 (47% identical), ZNF799 (47% identical), ZNF443 (47% identical), ZNF823 (46% identical), ZNF442 (45% identical), ZNF441 (44% identical), ZNF878 (44% identical), ZNF14 (43% identical), ZNF791 (43% identical), ZNF844 (36% identical), and 3 more.
Diseases named in the same sentence as ZNF700 in open-access papers:
ZNF700 is named in the same sentence as 7 diseases in open-access papers, as found by Europe PMC text mining. Sharing a sentence is not in itself a finding about the gene and the disease. The quoted sentences say what the papers report.
autoimmune disease (1 paper, 2015). A disorder resulting from loss of function or tissue destruction of an organ or multiple organs, arising from humoral or cellular immune responses of the individual to their own tissue constituents. "Autoantibodies to other zinc finger proteins were also frequently detected in cancer and autoimmune disease; however, there is a paucity of literature on autoantibodies specific to zinc finger proteins ZNF700 and ZNF768." (PMID 25875936, 2015).
colon cancer (1 paper, 2022). "However, in the current state of the research, there are still many ZFPs whose mechanisms of action in colon cancer are not fully understood, and more mechanisms need to be further studied, such as ZNF146, ZNF511, ZNF346, ZNF638, ZNF700, and ZNF768." (PMID 36358661, 2022).
colorectal cancer (1 paper, 2015). A primary or metastatic malignant neoplasm that affects the colon or rectum. "Our results indicate that zinc finger proteins ZNF346, ZNF638, ZNF700 and ZNF768 are suitable for use as capture antigens in a blood-based biomarker assay for colorectal cancer." (PMID 25875936, 2015). "In this study we assess the zinc finger proteins ZNF346, ZNF638, ZNF700 and ZNF768 as capture antigens for the detection of autoantibodies in colorectal cancer." (PMID 25875936, 2015). "In the current study, we validated the presence of autoantibodies to ZNF346, ZNF638, ZNF700 and ZNF768 in colorectal cancer in an independent and larger patient cohort using the well-established ELISA platform." (PMID 25875936, 2015). "We have previously identified autoantibodies to ZNF346, ZNF638, ZNF700 and ZNF768 in colorectal cancer patients using a 37,830-clone recombinant human protein array." (PMID 25875936, 2015).
Stroke (1 paper, 2023). Sudden impairment of blood flow to a part of the brain due to occlusion or rupture of an artery to the brain. "Co-expressed hub genes of EIF4E3, ZNF595, ZNF700, MATR3, ACKR4, ANXA3, SEPSECS-AS1, and RNF166 were significantly associated with AF-related stroke." (PMID 36952494, 2023). "Based on the results of DEG3 and ROC curves in GSE66724 and GSE58294, we filtered eight hub genes of AF-related stroke (AUC > 0.8), including EIF4E3, ZNF595, ZNF700, MATR3, ACKR4, ANXA3, SEPSECS-AS1, and RNF166." (PMID 36952494, 2023). "Hub genes EIF4E3, ZNF595, ZNF700, MATR3, ACKR4, ANXA3, SEPSECS-AS1, and RNF166 have potential as novel biomarkers and therapeutic targets in AF-related stroke." (PMID 36952494, 2023). "The hub genes of EIF4E3, ZNF595, ZNF700, MATR3, ACKR4, ANXA3, SEPSECS-AS1, and RNF166 may link AF and secondary stroke." (PMID 36952494, 2023).
cancer (2 papers, 2015 to 2023). A tumor composed of atypical neoplastic, often pleomorphic cells that invade other tissues. "Autoantibodies to ZNF700 were detected in sera of 19 out of 96 CRC patients (19.8%) and in 2 out of 35 non-cancer control samples (5.7%)." (PMID 25875936, 2015).
ZNF700 also shares sentences with these, for which no sentence is quoted: breast carcinoma (1 paper); Down syndrome (1).